IFI44 (interferon induced protein 44)
Diseases named in the same sentence as IFI44 in open-access papers (continued):
Sharing a sentence is not in itself a finding about the gene and the disease.
cancer (17 papers, 2011 to 2025). A tumor composed of atypical neoplastic, often pleomorphic cells that invade other tissues. "It is important to note that Il1rap, Ifi44, Timd4, Fabp3, and Eno 2 have been reported as potential therapeutic targets and potential prognostic biomarkers for several cancers." (PMID 41011134, 2025). "We then analyzed the expression of two well-known interferon-induced genes, IFIT3 and IFI44, using mRNA expression data from the Cancer Cell Line Encyclopedia." (PMID 36882786, 2023). "In a previous study, the investigation provided preliminary evidence that high expression of IFI44 was associated with poor prognosis in HNSC and other types of cancer." (PMID 33123469, 2020). "All results exhibited that IFI44 protein was mainly located in the cytoplasm and widely expressed in several human cancer sections and normal tissues." (PMID 33123469, 2020). "To further assess the role of IFI44/Met/Src axis in regulating cancer metastasis, we performed additional Western blotting analysis as well as migration and invasion assay." (PMID 29848298, 2018). "Further study on the interaction between IRF4 and the IFN-inducible genes including IFI27 and IFI44 may disclose the mechanism through which IRF4 confers resistance to IFN treatment of vial cancers by regulating their expression." (PMID 25207815, 2014). "Subsequently, we focused on a group of six candidate genes (Cd74, Lpl, Ifi44, Sat1, Fzd9 and Wwc1) that have been reported to be frequently regulated by epigenetic mechanisms and participate in the regulation of important signal pathways during cancer development and progression." (PMID 34836197, 2021). "However, the molecular functions of IFI44 in cancer cells remain to be explored." (PMID 31703415, 2019). "Consistent with the findings in human cancer cell lines, the canonical IFN signaling genes such as Isg15, Ifi44, Ifit3, and Ddx58 were induced at a significantly higher magnitude in Rad21-knockdown cells upon IFN-β stimulation." (PMID 36201246, 2022). "Induced ZNF395 expression led to the upregulation of genes known to play a role in cancer as well as a subset of interferon (IFN)-stimulated genes (ISG) involved in antiviral responses such as IFIT1/ISG56, IFI44 and IFI16." (PMID 24086395, 2013). "Interestingly, some of the factors such as a xylulokinase homologue (XYLB), the 2′-5′-oligoadenylate synthetase like (OASL) and the interferon-induced protein (IFI44) have not been so far linked to cancer and may represent markers of aneuploidy that are not linked to malignancy." (PMID 24548329, 2014). "Besides, the overexpression of IFI44 in the HNSC section was verified in three public microarray datasets (GSE107591, 45 normal vs. 167 cancer, P < 0.0001; GSE30784, 23 normal vs. 24 cancer, P = 0.0076; GSE138206, 12 normal vs. 6 cancer, P = 0.0023)." (PMID 33123469, 2020).
immune diseases (6 papers, 2014 to 2024). "Further, IFI44, as an immune-related gene, is involved in immune diseases, but the studies in tumors is insufficient." (PMID 34136486, 2021). "The expression and function of IFI44 and OAS2 still need further exploration and experimental verification, especially in chronic inflammatory and immune diseases." (PMID 37898694, 2023).
bacterial infection (3 papers, 2019 to 2022). "SOCS and USP18 proteins have been reported to promote bacterial infection, whereas few IFI44 proteins have been studied." (PMID 36189314, 2022). "However, most of the functions of IFI44 are unknown, and further investigation of its mechanisms in bacterial infection is a direction of interest." (PMID 36189314, 2022). "In our study, the expression of IFI44 and HERC5 were found to be up-regulated that means host system tried to resist bacterial infection." (PMID 31749827, 2019).
inflammatory myopathies (1 paper, 2023). "In addition, the IFN6 score (ISG15, LY6E, IFI44, IFI27, IFIT1, and OAS1) was higher in 13 DM patients than in 40 patients with inflammatory myopathies (no patients had SLE or MCTD)." (PMID 36979843, 2023).
IFI44 also shares sentences with these, for which no sentence is quoted: primary Sjögren syndrome (4 papers); non-small cell lung carcinoma (3); alcoholism (1); atherosclerosis (1); autoimmune uveitis (1); bacterial pneumonia (1); bovine respiratory disease complex (1); brucellosis (1); Cirrhosis (1); colorectal cancer (1); dengue (1); Dengue hemorrhagic fever (1); Epstein-Barr virus infection (1); H1N1 virus infection (1); hepatitis diseases (1); Hypercholesterolemia (1); limited scleroderma (1); lung adenocarcinoma (1); lung fibrosis (1); ovarian carcinoma (1); parasite infection (1); periodontitis (1); Pleural effusion (1); pneumonia (1); Primary immunodeficiency (1); prostate adenocarcinoma (1); psoriasis (1); respiratory infection (1); rheumatoid arthritis (1); scleroderma (1).
A further 7 diseases each share a sentence with IFI44 in 1 paper.